PPARG (peroxisome proliferator activated receptor gamma)
Diseases named in the same sentence as PPARG in open-access papers (continued):
Sharing a sentence is not in itself a finding about the gene and the disease.
osteosarcoma (36 papers, 2008 to 2025). A usually aggressive malignant bone-forming mesenchymal neoplasm, predominantly affecting adolescents and young adults. "Out of the differentially modulated genes, those implicated in stem cell and osteosarcoma biology, such as PPARG, ETS1, WNT1, WNT5B, SOX2, NANOG, POU5F1, nestin, and ALDH were chosen for further analysis." (PMID 22870217, 2012). "The combination of the peroxisome proliferator-activated receptor gamma (PPARγ) agonist pioglitazone and cisplatin for osteosarcoma treatment has been effective." (PMID 40864783, 2025). "For instance, PPARγ agonists enhance pro-apoptotic pathways (e.g., p21 and Bax), suppressing osteosarcoma growth, and improve therapeutic responses in high-risk NB by promoting differentiation and metabolic reprogramming." (PMID 40370434, 2025). "It has been shown that in human osteosarcoma, the pro-apoptotic effects exerted by Oridonin inhibition of the Nrf2 pathway require PPARG activation." (PMID 39654890, 2024). "PPARG can trigger cell apoptosis and suppress the growth of osteosarcoma cells by facilitating the terminal differentiation of osteoblasts." (PMID 39654890, 2024). "Here, we showed that PPARg antagonist inhibits the development of osteosarcoma both in vitro and in vivo." (PMID 36681687, 2023). "The mean PPARγ mRNA level in osteosarcoma tumors and tumor margin group was 0.24 ± 0.15 and 0.11 ± 0.07, respectively." (PMID 35922782, 2022). "In contrast to these pro-apoptotic actions of PPARγ agonists, the PPARγ agonist troglitazone increased cell proliferation and inhibited staurosporine-induced apoptosis in several osteosarcoma cell lines through Akt activation." (PMID 35954274, 2022). "The activation of PPARγ signaling has also been found to be a link in the mechanism of action of oridonin in inhibiting the tumor growth of osteosarcoma." (PMID 36033957, 2022). "The different between PPARγ mRNA level in GCT tumors compared to osteosarcoma (P = 0.006) and Ewing Sarcoma tumors (P = 0.0107) was statistically significant." (PMID 35922782, 2022). "Although the results of in-vitro studies on osteosarcoma cells favor the role of tumor suppressor of PPARγ, data of the current study showed the enhanced level of PPARγ in tumors with more severity." (PMID 35922782, 2022). "In agreement, in the current study the elevated PPARγ protein level was correlated with high grade, metastatic and recurrent tumors that were more prominent for osteosarcoma tumors." (PMID 35922782, 2022). "The mean PPARγ mRNA expression was significantly higher in bone tumors compared to healthy bone tissues, also the malignant tumors including osteosarcoma and Ewing sarcoma had the elevated level of PPARγ mRNA compared to GCT tumors." (PMID 35922782, 2022). "It has been reported that multiple PPARγ agonists can upregulate PTEN expression in many types of cancer cells including human osteosarcoma cells, hepatoma carcinoma cells, and lung adenocarcinoma cells." (PMID 37073266, 2021). "The miRNA was shown to play a crucial role in the progression of osteosarcoma in patients by targeting PPARγ." (PMID 33005638, 2020). "The endogenous PPARγ activator 15d-PGJ2 was also reported to induce ROS-mediated JNK activation which contributes to apoptosis in osteosarcoma." (PMID 30018246, 2018). "Low TIMP3 (Wnt target), and high CTGF (YAP target) and PPARγ expression suggest a more aggressive osteosarcoma sub-type with low Wnt and Hippo signaling, and a higher propensity to adipocytic differentiation as reflected by high PPARγ expression." (PMID 27528232, 2016).
osteosarcoma (continued). "This is probably because high TIMP3 and low CTGF and PPARγ expression indicates a more differentiated and less stem-like osteosarcoma sub-type with high Wnt and Hippo signaling." (PMID 27528232, 2016). "RNA-SEQ analysis reveals that the TZD rosiglitazone induces PPARγ targets and lipid metabolism genes in osteosarcoma cells, while reducing the expression of several cancer-related genes." (PMID 27528232, 2016). "This analysis recapitulates the antagonistic relationship described between Wnt and PPARγ signaling in normal bone, in the context of osteosarcoma development." (PMID 27528232, 2016). "As a hub ARG and a prognosis-related ARG, the effect of PPARG on macrophages in osteosarcoma remains unclear and is worth exploring further." (PMID 38217543, 2024). "Together, our results revealed that modulators of RARb, PPARg, LXRs and Rev-Erba inhibit osteosarcoma growth both in vitro and in vivo through the mTOR signaling pathway, suggesting that treatment with these NR modulators is a novel potential therapeutic strategy." (PMID 36681687, 2023). "Notably based on our data, PPARγ protein was localized in the cytoplasm of both osteosarcoma and Ewing sarcoma tumors." (PMID 35922782, 2022). "Furthermore, the PPARγ protein level was found to be expressed more in osteosarcoma (P < 0.0001), Ewing Sarcoma tumors (P < 0.0001) and GCT (P < 0.0001) tumors compared to normal bone tissues." (PMID 35922782, 2022). "In specific, GCT tumors expressed a significant lower level of PPARγ protein compared to osteosarcoma (P < 0.0001) and Ewing Sarcoma tumors (P < 0.0001); while the protein level of PPARγ protein was significantly higher in osteosarcoma tumors compared to Ewing Sarcoma tumors (P = 0.001)." (PMID 35922782, 2022). "Another study on osteosarcomas showed that activation of RXRα and PPARγ may synergistically inhibit tumor growth and cell proliferation, at least partially by inducing osteoblastic differentiation of osteosarcoma cells." (PMID 35406808, 2022). "Recently, accumulating data has suggested that the differentiation promotion therapy with differentiation agents, including PPARγ agonists, in osteosarcoma might be a potential theranostic strategy and has been extensively examined." (PMID 32630668, 2020). "This led us to hypothesize that adipogenesis may be induced in osteosarcomas via targeted stimulation of peroxisome proliferator-activated receptor gamma (PPARγ), a nuclear receptor that activates genes essential for fat formation." (PMID 27528232, 2016). "Osteosarcoma 143B and adenocarcinoma A549 cells express the PPARγ gene." (PMID 27129022, 2016). "Increasing evidence suggests that activation of PPARγ may be explored as a possible intervention in osteosarcoma." (PMID 20182546, 2010). "Furthermore, PPARγ agonists have the potential to induce terminal differentiation in osteosarcoma cells." (PMID 20182546, 2010). "Peroxisome proliferator activated receptor (PPAR)γ/retinoid X receptor (PPARγ/RXR) agonists may induce differentiation in osteosarcoma, despite critical blocks to the normal bone morphogenetic protein (BMP)-regulated pathways." (PMID 18782081, 2008). "Accordingly, in osteosarcoma, TUBB and MAP3K5 were believed to function as tumor suppressors, actively inhibiting tumor growth and progression, while TERT and PPARG appear to act as cancer promoters, exacerbating the development of osteosarcoma." (PMID 39980969, 2024). "Four ARGs-BRMS, COL4A2, FGF2, and OGT-were used to develop an RFS-predicting model, whereas seven ARGs-CD24, FASN, MMP2, EIF2AK3, ID2, PPARG, and PIK3R3-were used to develop an OS-predicting model in patients with osteosarcoma." (PMID 38217543, 2024).
osteosarcoma (continued). "In conclusion, our study revealed that four NR modulators, namely, the RARb antagonist LE135, PPARg antagonist T0070907, LXR agonist T0901317 and Rev-Erba agonist SR9011, effectively inhibit the growth of osteosarcoma in vitro and in vivo." (PMID 36681687, 2023). "The immunofluorescence and western blotting results showed that the RARb antagonist LE135, PPARg antagonist T0070907, LXR agonist T0901317 and Rev-Erba agonist SR9011 reduced the KI-67 and PCNA protein levels in all three osteosarcoma cell lines." (PMID 36681687, 2023). "A previous study revealed that gene PPARG, gene IGHG3, and gene PDK1 were correlated with osteosarcoma." (PMID 34188683, 2021). "It was shown that 20 dynes/cm2 shear force significantly induces PPARδ and PPARγ protein expressions after 4, 8 and 24 h of stimulations in human MG63 osteosarcoma cells compared to the untreated controls." (PMID 32630668, 2020). "Low Wnt activity, high levels of PPARγ and low Hippo pathway activity characterize the CSC fraction of the osteosarcoma cell population, where high Sox2 expression antagonizes the Hippo pathway, represses the Wnt pathway and regulates PPARγ expression." (PMID 27528232, 2016). "The Sca-1- expressing CSC population of osteosarcoma that are responsible for tumor seeding, recurrence and metastasis is more responsive to TZD treatment These cells have elevated expression of PPARγ which probably accounts for this effect." (PMID 27528232, 2016). "The activity of these reporters was determined in human osteosarcoma (U2OS) cells, which express negligible levels of endogenous PPARγ protein, but display a robust response upon overexpression of the protein." (PMID 23696875, 2013). "Research showed that PPARG antagonists could abnormally activate the PI3K/AKT/mTOR and ERK/mTOR pathways in osteosarcoma cells and effectively inhibited the growth of OS in vivo and in vitro." (PMID 40070565, 2025). "In osteosarcoma tumor microenvironment-related literature, we take notice that the connection between the score of immunity and survival state has been investigated, and C3AR1, PPARG, PDK1, IGHG3, and C1Q are recognized as prognostic biomarkers." (PMID 36844870, 2023). "Despite of significant elevation in the PPARγ protein in high grade osteosarcoma tumors (P = 0.012), no specific difference was observed between low and high grade Ewing Sarcoma tumors." (PMID 35922782, 2022). "The PPARγ protein level was expressed non-significantly in recurrent osteosarcoma tumors; while significantly in recurrent Ewing Sarcoma tumors (P = 0.008) compared to tumors without recurrence in each group." (PMID 35922782, 2022). "The PPARγ mRNA level in recurrent osteosarcoma (0.31 ± 0.18) and Ewing Sarcoma (0.30 ± 0.19) tumors was increased compared to the non-recurrent osteosarcoma (0.22 ± 0.13) and Ewing Sarcoma (0.20 ± 0.08) tumors; while it was not statistically significant." (PMID 35922782, 2022). "PPARγ-null osteosarcoma cells do not respond to TZDs, thereby highlighting that PPARγ is essential for anti neoplastic effects of TZDs." (PMID 27528232, 2016). "By utilizing TZDs that function as high-affinity agonists of PPARγ, we demonstrate that TZD-induced activation of this nuclear receptor exerts anti-proliferative effects via promoting adipogenic differentiation in osteosarcoma cells." (PMID 27528232, 2016). "Therefore, PDK1 and PPARG may become prognostic genes in osteosarcoma and may be targets for subsequent regulation of ICI-related genes for osteosarcoma treatment." (PMID 39654890, 2024). "The inhibitory effects of the RARb antagonist LE135, PPARg antagonist T0070907, LXR agonist T0901317 and Rev-Erba agonist SR9011 were all abolished in the corresponding NR-knockout cells, indicating that the NR modulators specifically target the corresponding NRs to inhibit osteosarcoma cell growth." (PMID 36681687, 2023).
osteosarcoma (continued). "Interestingly, chemotherapy-received osteosarcoma (P = 0.039) and Ewing Sarcoma (P = 0.004) tumors illustrated higher level of PPARγ protein to the tumors without any history of chemotherapy, respectively." (PMID 35922782, 2022). "Thus these results demonstrate that the TZD effects on osteosarcoma cells are mediated by PPARγ activation and not by unrelated or off-target mechanisms." (PMID 27528232, 2016). "Moreover, osteosarcoma patients suffering from metastasis (0.36 ± 0.18) expressed higher level of PPARγ mRNA level compared to non-metastatic patients (0.19 ± 0.1) (P = 0.0051); while the difference between Ewing Sarcoma metastatic and non-metastatic tumors was not significant." (PMID 35922782, 2022). "We found that chemical inhibition of RARb and PPARg (LE135 and T0070907) and activation of LXRs and Rev-Erba (T0901317 and SR9011) significantly suppressed osteosarcoma cell proliferation but not osteoblast proliferation." (PMID 36681687, 2023). "Four chemicals, namely, the RARb antagonist LE135, PPARg antagonist T0070907, LXR agonist T0901317 and Rev-Erba agonist SR9011, can inhibit the growth of all three osteosarcoma cell lines without affecting the growth of normal osteoblasts." (PMID 36681687, 2023). "Our results suggested that 4 NR modulators, namely, the RARb antagonist LE135, PPARg antagonist T0070907, LXR agonist T0901317 and Rev-Erba agonist SR9011, can significantly suppress osteosarcoma cell growth without exerting toxic effects on normal osteoblast cells." (PMID 36681687, 2023). "However, in the present results, only PPARδ and PPARγ, but not PPARα, expressions were increased in MG63 osteosarcoma cells in response to high shear force stimulation, and further results found that only PPARδ is involved in mediating SCD-1 upregulation of high shear force stimulation." (PMID 32630668, 2020). "Hence, changes in ROS, PPARγ-dependent and PPARγ-independent activities of 15d-PGJ2, and altered monosaturated lipogenesis each represent plausible combinatorial mechanisms for the selective action of V-BAP against osteosarcoma cells when compared with non-transformed MSCs." (PMID 33289496, 2021).
osteoarthritis (35 papers, 2007 to 2026). A noninflammatory degenerative joint disease occurring chiefly in older persons, characterized by degeneration of the articular cartilage, hypertrophy of bone at the margins and changes in the synovial membrane. "In summary, we demonstrated that PPARγ activation inhibits chondrocyte ferroptosis in osteoarthritis and that this chondroprotective effect is associated with the activation of Pink1/Parkin-dependent mitophagy." (PMID 37620972, 2023). "Three out of the 166 enriched RBPs (PRDM1, RUNX3 and PPARG) were also DE in our dataset and have been extensively linked to osteoarthritis." (PMID 35088088, 2022). "As for the specific molecular mechanisms, studies have shown that stress and inflammation can cause inhibition of the PPAR-γ pathway (peroxisome proliferator-activated receptor-gamma), as in osteoarthritis." (PMID 35495685, 2022). "In contrast to our findings, cartilage‐specific deletion of PPARγ using Col2a1‐Cre caused severe osteoarthritis in 14‐month‐old mice, associated with synovial inflammation and expression of catabolic factors." (PMID 33048436, 2020). "They propose thiazolidinediones as promising disease‐modifying agents in osteoarthritis due to the predicted role of the direct drug target PPARG in the context of osteoarthritis progression." (PMID 39888210, 2025). "The Hulth model group had significant osteoarthritis manifestations, and the pioglitazone group improved the changes of these indexes, indicating that PPARγ agonists have the effect of attenuating osteoarthritis in rats." (PMID 37620972, 2023). "As a rescue mechanism to alleviate osteoarthritis, the chondroprotective effect of PPARγ was elucidated in the present study." (PMID 37620972, 2023). "Past reports and our previous research have shown that PPARγ is a key regulator in maintaining cartilage health and has a chondroprotective role in osteoarthritis." (PMID 37620972, 2023). "Based on the effectiveness, the target DNMT1 was selected to identify the active constituents of DD in ameliorating osteoarthritis, presumably by preservation of PPARγ expression." (PMID 36506533, 2022). "In this study, we observed the PPARγ pathways is involved in the protective effects of osteoarthritis by reducing inflammatory reaction." (PMID 35842709, 2022). "Another anti-inflammation signaling pathway triggered by BA is through the activation of peroxisome proliferator-activated receptor gamma (PPARγ) as shown in the IL-1β-induced inflammation of osteoarthritis chondrocytes." (PMID 34721992, 2021). "Consistent with previous studies, osteoarthritis was reduced by deletion of PPARγ, and if anything, it was mild in the aged control mice." (PMID 33048436, 2020). "Chondrocytes stimulation with interleukin-1β (IL-1) leads to the recruitment of EGR1 to Pparg promoter and downregulates its expression, preventing the protective effect of PPARγ in osteoarthritis." (PMID 32121305, 2020). "Strikingly, deletion of PPARγ exacerbates the development of cortical porosity but attenuates osteoarthritis with aging." (PMID 33048436, 2020). "Previous reports also demonstrated that BA inhibited IL-1β-induced inflammation via activating PPARγ in osteoarthritis chondrocytes." (PMID 29666569, 2018). "Recently, the pivotal gene for energy metabolism, PPARG, has been linked with some kinds of immune-related diseases, such as HCV/HIV infection, osteoarthritis and acne vulgaris." (PMID 27047549, 2016). "Similarly, 5aza, a DNA methylase inhibitor, was found to attenuate the methylation of the PPARγ promoter region, thereby promoting PPARγ expression, maintaining homeostasis in chondrocytes, and delaying the osteoarthritis progression." (PMID 37986543, 2024). "PPARγ deficiency leads to spontaneous osteoarthritis, and notably, PPARγ expression is reduced in human osteoarthritic cartilage compared with normal cartilage." (PMID 37620972, 2023). "PPARγ activation alleviated osteoarthritis through the Nrf2/NLRP3 pathway." (PMID 37905351, 2023).